INS (insulin)
Diseases named in the same sentence as INS in open-access papers (continued):
Sharing a sentence is not in itself a finding about the gene and the disease.
Insulin resistance (continued). "On the other hand, laboratory indicators such as postprandial blood glucose, fasting insulin and C peptide, electrolytics, and hormone levels were not examined in this study, therefore insulin resistance and endocrine hormone disorder cannot be evaluated." (PMID 34956330, 2021). "Insulin resistance state occurring when cells in muscles, fat and liver do not respond well to insulin action." (PMID 33578702, 2021). "Additionally, HDAC4 and HDAC5 can also suppress the GLUT4 gene and contribute to insulin resistance, while HDAC7 has been reported to contribute to the impairment of insulin secretion and trigger β-cell apoptosis." (PMID 34071497, 2021). "Here, we systematically analyzed the contribution of factors that affect maternal insulin resistance during gestation including time on WSD, diet switching to/from chow to WSD, age, and parity on maternal insulin levels during third trimester glucose tolerance testing." (PMID 34155315, 2021). "Glp-1 stimulates insulin secretion from pancreatic β-cells, so the higher levels of circulating Glp-1 in HFHSD-fed mice may be a compensatory response to insulin resistance at the prediabetic state, which leads to hyperinsulinaemia." (PMID 34552271, 2021). "Some studies suggested that insulin resistance was not an essential determinant in CFRD compared with insulin secretion." (PMID 33659254, 2021). "Insulin resistance occurs when the cells in the muscles, fat, and liver do not respond appropriately to insulin and cannot uptake glucose from the blood for deriving energy." (PMID 33928135, 2021). "Insulin resistance (IR) is defined as a state when the physiological amount of insulin does not evoke proper action, which is glucose utilization by peripheral tissues." (PMID 34207541, 2021). "Moreover, acute insulin resistance as estimated by HOMA-IR tertile was significantly higher in obese, those with heart failure (Killip class >1), and higher plasma insulin level, CPK-MB, and fasting blood glucose level." (PMID 34041280, 2021). "Insulin resistance means that the body is not sensitive to insulin, the generation of normal insulin dose cannot maintain normal biological effects, namely the insulin‐sensitive cells mediates glucose uptake and disposal to insulin resistance." (PMID 34026064, 2021). "The phosphorylation of serine and threonine residues in IRS has a negative impact on insulin signaling and contributes to pathological insulin resistance." (PMID 33672754, 2021). "Overnutrition causes hyperactivation of mTORC1-dependent negative feedback loops leading to the downregulation of insulin signaling and development of insulin resistance." (PMID 33551450, 2021). "The glucose consumption of insulin-resistant LO2 cells is also lower than LO2 cells without insulin resistance." (PMID 34122092, 2021). "Insulin resistance means that the normal insulin concentration is not sufficient to produce the desired response to its target tissues." (PMID 33718264, 2021). "Moreover, insulin-resistant adipocytes mobilize TAG (triacylglycerol) stores, which, in turn, induce lipid-mediated insulin resistance in the liver in an IL-1β-dependent manner." (PMID 34299048, 2021). "This supports the contention that for individuals most at need for an intervention to maintain insulin sensitivity/prevent insulin resistance, it is the PAE as opposed to chronic effect of exercise on insulin sensitivity that is the more relevant to consider." (PMID 34386716, 2021). "As such, the application of the ePRSs allowed us to investigate the role of variations in insulin metabolism in specific tissues in individuals regardless of insulin resistance status." (PMID 34732766, 2021). "As one of the insulin-sensitizing fatty factors, APN is secreted by fat cells to improve insulin resistance and attenuate hyperglycemia as well as impair RANKL-stimulated RAW264.7 cells through its receptors as AdipoR1, AdipoR2, and T-Cadherin and its downstream factors of cohesive protein APPL1." (PMID 36632609, 2021).
Insulin resistance (continued). "While these data indicate marked insulin resistance, suggesting even after 6 weeks of ad libitum BYL-diet treatment BYL was still effective in suppressing insulin signaling, we next assessed the ability to lower blood glucose following a more physiological meal challenge." (PMID 33503847, 2021). "Our results suggest that the interplay between the KCNQ1 ACC haplotype and alcohol consumption increases the risk of T2DM resulting from pancreatic β-cell dysfunction, rather than a change in insulin resistance and/or insulin sensitivity." (PMID 34750480, 2021). "T2DM is characterized by elevated fasting plasma glucose (FPG), insulin resistance and relative lack of insulin." (PMID 34072748, 2021). "In this negative feedback system, insulin secretion is controlled and glucose levels remain within the normal range as long as subjects are able to overcome insulin resistance by increasing insulin secretion." (PMID 34360563, 2021). "Liver insulin resistance (LIR) is manifested by impaired insulin-mediated suppression of hepatic glucose production (HGP), while muscle insulin resistance (MIR) is characterized by decreased insulin-mediated glucose disposal." (PMID 34277687, 2021). "In addition to skeletal muscle, liver insulin resistance results in elevated basal endogenous glucose production (EGP) and reduced insulin suppression of EGP, further contributing to higher plasma glucose concentrations." (PMID 33387681, 2021). "In addition to the central nervous system, PKCζ was also related to peripheral insulin resistance, suggesting a unique role of this PKC isoform in the regulation of insulin sensitivity by ceramides." (PMID 34069652, 2021). "Any impairment of the relationship between INS and INSR will lead to insulin resistance." (PMID 33549051, 2021). "Insulin resistance is a condition in which tissues are unable to respond to normal plasma insulin level, with tissue-specific functional consequences." (PMID 34071721, 2021). "Although the obese PCOS patients had lower levels of high molecular weight adiponectin (P = 0.03) than the normal weight PCOS individuals, the level of insulin and insulin resistance was not different in them (P = 0.13, 0.13)." (PMID 33750349, 2021). "Fasting glucose and insulin levels, as well as glycated haemoglobin (HbA1c), insulin-like growth factor (IGF-1), the homeostatic model assessment for insulin resistance (HOMA) and the quantitative insulin sensitivity check index (QUICKI) did not change significantly." (PMID 34117276, 2021). "As established earlier, the ePRS-IRs measure variation in insulin glucose metabolism and not metabolic states such as insulin resistance." (PMID 34732766, 2021). "Following HFHSD, the Rag1-KO mice became obese, developed impaired glucose tolerance and insulin resistance, and showed non-compensatory stimulated insulin release despite being hyperinsulinemic." (PMID 33670429, 2021). "Plasma insulin is usually monitored together with HbA1c and FPG to discern insulin resistance." (PMID 35083188, 2021). "Indeed, it was reported that SGLT2 inhibitors improved muscle insulin sensitivity, although it enhanced endogenous glucose production, and that SGLT2 inhibitors improved insulin resistance in skeletal muscle and accelerated lipolysis in adipose tissues." (PMID 33807522, 2021). "Among the biochemical parameters most used in research, due to their reliability in evaluating the therapeutic efficacy of different nutraceuticals in the control of metabolic diseases, are HbA1c, insulin resistance (calculated by the HOMA-IR index), fasting glucose, and insulin." (PMID 33430470, 2021). "Saturated fatty acids promote insulin resistance versus polyunsaturated fatty acids that do not affect insulin resistance but promote insulin sensitivity." (PMID 34299261, 2021). "T2DM, on the other hand is attributed to a combination of insulin resistance and a lack of / inadequacy of insulin secretory response." (PMID 34225729, 2021).
Insulin resistance (continued). "Nutrient-induced toxicity due to overnutrition can lead to insulin resistance in tissues like skeletal muscle and heart tissues, which normally respond to insulin for glucose uptake." (PMID 33557218, 2021). "The metabolic improvements were observed both in rats that were normo‐insulinemic/normoglycemic and that had normal insulin sensitivity, and in rats with insulin resistance that were hyperinsulinemic (but not hyperglycaemic)." (PMID 33855218, 2021). "Within 8 weeks of HFHSD, B6 mice became obese, developed impaired glucose tolerance and insulin resistance, and despite being hyperinsulinemic displayed non-compensatory insulin release, at least in part, due to reduced expression of syntaxin-1A." (PMID 33670429, 2021). "BP, HbA1c, and C peptide in patients with insulin resistance were significantly different between those with and without insulin treatment." (PMID 34272768, 2021). "Our data revealed that the intake of a restricted HFD results in normal insulin values but higher glycemia, suggesting the persistence of insulin resistance, which is related to the type of diet rather than to the amount of weight loss or the body fat content." (PMID 34206176, 2021). "Fat cell enlargement is an independent marker of insulin resistance; however, no significant change in adipocyte insulin sensitivity was seen at the 4-week visit despite the marked reduction in cell size." (PMID 34086911, 2021). "Taken together, HS could be a promising target for drug development to improve insulin resistance via BMP4–FGF1-dependent adipogenic differentiation, and also to increase insulin secretion from β-cells." (PMID 34310946, 2021). "L-IDE-KO mice exhibit higher fasting and non-fasting glucose levels, glucose intolerance, and insulin resistance, despite normal plasma insulin levels." (PMID 33477364, 2021). "Interestingly, despite normal glucagon secretion at 2 months of age alphaIRS2KO mice displayed slightly reduced body weights, insulin resistance, and reduced AKT phosphorylation in response to insulin." (PMID 33839150, 2021). "Oleate increases insulin signaling and reduces NPY expression and linolenic acid may reduce insulin resistance through the increase in fatty acid oxidation in agreement with our data showing augmented Cpt1a expression in ND IRS2−/− mice." (PMID 34440853, 2021). "Insulin resistance results in a dysfunctional insulin-stimulated GLUT4 pathway in the skeletal muscle of obese, T2DM, and GDM patients; however, the non-insulin dependent pathway seems to remain intact in obesity and insulin resistant stages." (PMID 33870263, 2021). "Nevertheless, human studies have not shown a consistent relationship between insulin sensitivity and serum chemerin levels and its exact role in whole body insulin resistance remains controversial." (PMID 34966295, 2021). "Notably, although NGT women exhibited higher insulin sensitivity than NGT men, prediabetic and newly diagnosed T2DM women have the same degree of insulin resistance than their male counterparts." (PMID 33676510, 2021). "The pathogenetic relationship between the GH secretion and insulin secretion both during glucose loading and in other conditions represented of insulin resistance is not in doubt, but requires further study." (PMID 33586392, 2021). "Homeostatic model assessment of insulin resistance (HOMA-IR) did not associate with either cardiovascular endpoint in any model and smoking did not increase the risk conferred by high fasting insulin levels." (PMID 34746266, 2021). "Individuals in Q4-Ln Homeostatic model assessment- Insulin Resistance (HOMA-IR) and Q1- Quantitative Insulin Sensitivity Check Index (QUICKI) also presented with increased risk for all-cause-mortality (HR = 1.2, 95%CI 1.04–1.4; and HR = 1.2, 95% CI 1.04–1.4, respectively)." (PMID 33957929, 2021).
Insulin resistance (continued). "Our study demonstrated that severe insulin resistance estimated using HOMA-IR and insulin concentration and high glycemic level estimated using HbA1c and 2h-PG were negatively associated with cognitive function in key domains except for verbal fluency, especially among participants without obesity." (PMID 34966358, 2021). "Moreover, phosphorylated Akt‐mediated insulin signal transduction and translocation of glucose transporter type 4 (GLUT4) were suppressed by HUA and were related to insulin resistance and impaired glucose uptake in cardiomyocytes." (PMID 34053175, 2021). "Persons who develop T2DM generally have prediabetes and insulin resistance (IR), a situation in which the body's cells do not respond normally to insulin." (PMID 35083188, 2021). "Collectively, our findings show that short-term treatment with TGFβ1 does not appear to influence insulin signalling or promote insulin resistance in myotubes." (PMID 34707569, 2021). "Insulin resistance is a central aspect in the pathophysiology of NAFLD; therefore, interventions aiming at the improvement of insulin sensitivity may be preferable." (PMID 34201382, 2021). "Although we did not measure insulin levels in study animals; however, the ratios indicate an onset of insulin resistance in the HF + STZ group and a reversal in the HF + STZ + IHZ group." (PMID 34155273, 2021). "High IL-10 levels may also increase insulin sensitivity by ameliorating the inflammatory responses to TNF-α and IL-6, which contribute to insulin resistance in PCOS." (PMID 34233746, 2021). "Type 2 diabetes (T2D) is a chronic metabolic disorder characterized by persistent hyperglycemia, insulin resistance, and a relative lack of insulin." (PMID 34575035, 2021). "The applied training in the form of NW with the intensity at which the maximal oxidation of fatty acids occurred, did not affect the level of glucose, insulin or insulin resistance indices (HOMA-IR and Quicki) in the studied group." (PMID 34539448, 2021). "Some NAFLD markers improved in both intervention groups (high-density lipoprotein, ALT, AST), but there was no change in glucose, insulin, and insulin resistance." (PMID 34357000, 2021). "Insulin resistance is a decrease in the biological function of insulin, irrespective of the serum concentration." (PMID 34754676, 2021). "Ginger could also significantly reduce fasting plasma insulin and HOMA-IR, showing an overall improvement in lipid profile, as well as insulin resistance." (PMID 34567218, 2021). "Insulin resistance is a condition in which the body fails to properly use insulin to regulate glucose metabolism." (PMID 33935964, 2021). "Type 2 diabetes mellitus (T2DM) is characterized by hyperglycemia, a relative lack of insulin and insulin resistance, and is a chronic metabolic disease." (PMID 34889226, 2021). "Based on the proposed effects of CRTC2/3 on CXCL1/2 expression and insulin resistance, we evaluated whether depletion of CRTC2/3 in adipose tissue modulates the effects of HFD on insulin signaling and glucose metabolism." (PMID 34686752, 2021). "Unlike T1DM being characterized by loss of insulin-producing cells, T2DM is typified by insulin resistance where cells, especially muscle and adipose tissue, no longer respond to insulin appropriately, which lowers the glucose clearance from the blood." (PMID 33800470, 2021). "Several measures of insulin sensitivity were then utilized to assess plasma glucose and insulin values from an oral glucose tolerance test (OGTT) to determine if the ad libitum pigs developed insulin resistance." (PMID 34737972, 2021). "However, the inhibition of insulin/IGF-1 signaling impairs cellular glucose uptake and enhances the generation of insulin resistance." (PMID 34476533, 2021). "Ang-II hinders the insulin-mediated activation of PI3K signaling, leading to insulin resistance." (PMID 34203830, 2021).
Insulin resistance (continued). "Considering that impaired hepatic insulin signaling plays an important role in NAFLD development, in order to evaluate insulin resistance, animals were challenged with an intraperitoneal insulin bolus determining Akt activation (phosphorylation on Serine 473) or saline." (PMID 34684533, 2021). "Studies conducted among patients with SCH confirm the lack of impact of levothyroxine treatment on the results of the glucose tolerance test and insulin resistance measured by indirect methods, such as HOMA-IR or quantitative insulin sensitivity check index (QUICKI)." (PMID 34880913, 2021). "Commonly, gestational diabetes develops if insulin secretion does not increase sufficiently to counteract the insulin resistance." (PMID 33467592, 2021). "Administration with HPLP or RSG for six weeks, HPLP and RSG group mice exhibited declined serum glucose levels, insulin levels, and HOMA-IR index (p < 0.01), indicating that PLP (100 mg/kg body weight) could improve insulin resistance in db/db mice." (PMID 33794128, 2021). "Thiamine treatment also decreased hyperglycemia and increased the glycogen content of the liver, but it did not improve insulin sensitivity, suggesting that steatosis can be addressed independently of targeting insulin resistance." (PMID 33608323, 2021). "In a cross-sectional study on the impact of insulin resistance and hypertriglyceridemia, non-Hispanic Whites and African Americans displayed greater insulin sensitivity compared to Hispanic White, East Asian, and South Asian." (PMID 34307250, 2021). "Nevertheless, in this study’s subjects who were not exposed to insulin, HOMA IR (%), an index of insulin resistance, did not affect the association between Δglucagon and HbA1C." (PMID 34199839, 2021). "Although insulin or HOMA-IR failed to indicate the significance in the multiple stepwise regression analysis, insulin resistance or metabolic syndrome was potentially associated with RLP-C." (PMID 34429062, 2021). "In addition, TNFα induces insulin resistance through serine phosphorylation of IRS-1, with consequent impairment of normal insulin signaling." (PMID 33805912, 2021). "Nevertheless, this study adequately set apart T2DM patients with insulin resistance who do not need insulin and only use oral antidiabetic drugs from patients who need insulin and present MCI." (PMID 34577866, 2021). "Insulin resistance is considered a pathological condition in which cells do not react efficiently to insulin stimulation." (PMID 34717724, 2021). "Five studies analyzed the effect of HIIT in comparison with moderate-intensity exercises or a control group on metabolic parameters, such as serum insulin levels, fasting glucose, TG, total cholesterol, LDL-c, HDL-c, and homeostatic insulin resistance (HOMA-IR)." (PMID 33465123, 2021). "Interestingly, strong negative associations between the PC, PE, PI, Cer and SM are observed with both parameters allowing to assess insulin resistance, namely HOMA-IR and fasting insulin." (PMID 34684461, 2021). "Several quantitative tools have been used to assess insulin sensitivity and insulin resistance, but there is still no consensus of standards in the pediatric population." (PMID 34485526, 2021). "This lack of consideration for the dynamics and insulin values make it difficult to detect early deterioration in individuals’ responses indicative of insulin resistance." (PMID 33788828, 2021). "Glucose tolerance tests (GTT) and insulin tolerance tests (ITT) also indicated that HuRLKO mice exhibited improved glucose tolerance and insulin resistance when fed HFD, which was confirmed by insulin-stimulated AKT Ser473 analysis in liver, skeletal muscle, and adipose tissue." (PMID 33664225, 2021). "As described, ROS affect insulin action in two ways: i) insulin-induced H2O2 formation is essential for mediating the insulin message to downstream targets, and ii) ROS are also involved in the development of insulin resistance and T2D." (PMID 33893069, 2021).